GFAP (glial fibrillary acidic protein)
Diseases named in the same sentence as GFAP in open-access papers (continued):
Sharing a sentence is not in itself a finding about the gene and the disease.
tumor (continued). "This suggests that GFAP+ monocyte numbers might reflect various tumour factors, such as size and speed of growth." (PMID 33501422, 2021). "Moreover, the staining intensity of GFAP was significantly higher in peritumoral regions compared to the tumor mass (p = 0.024), where fewer GFAP-positive cells were observed in the tumor mass compared to the contralateral healthy brain tissue." (PMID 34441246, 2021). "Type A cultures form tumor spheres, grow as intracranial xenografts and express astroglial and stem cell-related genes including GFAP (Glial Fibrillary Acidic Protein), SOX2 (SRY (sex determining region Y)-box 2) and PDGFRA (Platelet Derived Growth Factor Receptor α)." (PMID 34021259, 2021). "In addition, glial fibrillary acidic protein (GFAP) in the astrocytic component of the tumor was diffuse distribution." (PMID 34018072, 2021). "Consequently, our results combined with the available literature, make it hypothetically possible to evaluate the primary tumour of metastases with a primary-tumour-specific protein in GFAP+CD16+ monocytes." (PMID 33501422, 2021). "However tumor cells were revealed positivity for vimentin, soluble protein-100, and alpha-thalassemia/mental retardation syndrome X, GFAP strong positive in the cytoplasm." (PMID 34713831, 2021). "Immunohistochemical staining revealed there were many GFAP positive tumor cells (B5)." (PMID 33391433, 2021). "Most SEGA tumor cells presented immunoreactivity for GFAP and S100." (PMID 34065573, 2021). "Our results suggest the hypothesis that other cell types may be responsible for this increase in ALDH1A2 expression, as cells which co-stain for GFAP, a tumor cell, and reactive astrocyte markers were found in GBM tumors (data not shown)." (PMID 34572134, 2021). "The three-dimensional tumor cell sphere also allows us to observe the phenomenon more intuitively: GFAP+ Schwann cells destroy the sphere and enhance tumor invasion by promoting the separation of individual cells, forming linear cell chains, and inserting cells to destroy cancer cell contacts." (PMID 34572820, 2021). "The histological examination of the lesion biopsy documented a GFAP+ highly cellular neoplasm, with no mutation on SMARCB1 gene." (PMID 34906194, 2021). "This type of tumor demonstrates strong immunoreactivity for GFAP, S100, and Olig2." (PMID 34065573, 2021). "However, tumour volume correlated to the percentage of GFAP+CD16+ monocytes for both GBM (r = 0.215; P = 0.010) and brain metastasis (r = 0.504; P = 0.010)." (PMID 33501422, 2021). "A limited number of spindle tumor cells was positive for GFAP and podoplanin in all cases." (PMID 33576087, 2021). "The KMO protein expression was localized in GFAP+ cells in tumor tissue." (PMID 34440798, 2021). "Numerous GFAP/vimentin double-positive cells aligned at the tumor border (PT)." (PMID 34441246, 2021). "Although there was no direct association with the tumours positivity for GFAP and there only was an association with size in GBM, these results suggest that the GFAP in these monocytes is derived from both the tumour and the surrounding damaged brain tissue." (PMID 33501422, 2021). "However, 62 tumours that showed a co-expression of GFAP and cytokeratin reoccurred significantly less frequently than those that only expressed one or no intermediate filament (5/62 vs. 47/264)." (PMID 33001343, 2021). "In addition, astrogliosis, which produces GFAP+ cells under pathological conditions such as tumor and various injuries in the adult brain, is also reported to use the same ligands and receptors as those used in normal embryonic astrogenesis." (PMID 32341445, 2020).
tumor (continued). "Non-histone chromosomal protein HMG-17 (HMGN2), thymosin beta-4 (TMSB4X), 10 kDa heat shock protein (HSPE1), and the ratio between citrullinated/uncitrullinated GFAP fragment 388–432 showed significantly higher levels in ST-EPs, therefore marking the ST tumor location." (PMID 32183175, 2020). "GFAP-positive astrocytes appeared as a dense cell population encircling the tumor." (PMID 32190011, 2020). "High levels of GFAP can correlate with trauma, inflammatory, and tumor pathologies." (PMID 32183175, 2020). "Next, we asked whether GFAP+ enteric glia depletion could be impacting tumor development through effects on tumor features such as angiogenesis or tumor cell proliferation and death." (PMID 33282743, 2020). "Altogether, these data indicate that the absence of GFAP+ enteric glia has a limited impact on the properties of established tumors, suggesting that the GFAP+ glial cells may exert their pro-tumorigenic function early in tumor development." (PMID 33282743, 2020). "Interestingly, the ratio of the monocitrullinated/uncitrullinated form of the fragment 388-432 of GFAP (5207.74/5206.74, [M+H]+ monoisotopic masses) showed statistically significant and different results (p value < 0.0001) based on tumor localization." (PMID 32183175, 2020). "The data of immunofluorescence colocalization showed that there were a few cells in GBM samples with co-staining of LSP1 and glial fibrillary acidic protein (GFAP), which may imply a tumor cell-related LSP1 expression in GBM." (PMID 32003759, 2020). "To further investigate the role of GFAP+ enteric glia in early tumor development, we examined the number and grade of precancerous dysplastic lesions present in the colons of non-depleted control mice and enteric-glia-depleted mice six weeks after AOM/DSS induction." (PMID 33282743, 2020). "Staining for GFAP (glial fibrillary acidic protein) is predominantly positive in the tumor tissue." (PMID 32103286, 2020). "Importantly, expression of the stemness marker Nestin was decreased and expression of the differentiation marker GFAP was increased in tumor tissues formed from ARS2- or MAGL-knockdown GSCs." (PMID 32532977, 2020). "Indeed, after tumor growth, we observed an increase in GFAP expression only in the brain of mice receiving necrotic extracts." (PMID 32290386, 2020). "When MRI images at PID8 were compared with RNAscope images at PID9, the hyperintense signal on the MRI (aligned in red) extended beyond the area of dense tumor cells (aligned in blue) and included a large part of a GFAP+ astrogliotic rim around the dense tumor core as well (aligned in red)." (PMID 32977526, 2020). "Compared with the GBM mono-culture, reactive astrocytes promoted the upregulation of GFAP and vimentin proteins in the tumor microenvironment and possibly formed a functional barrier called a glial scar, thus increasing GBM chemoresistance, that needs to be further investigated." (PMID 32998285, 2020). "Higher preoperative GFAP serum levels also correlated with increased tumor volume and necrosis." (PMID 32650387, 2020). "We showed that xenograft tumors maintained the major histologic and key immunophenotypic features of the original tumor, with the exception of differentiation degree, which showed decreased GFAP expression in the propagated xenograft tumors compared with the corresponding original patient tumors." (PMID 31908598, 2020). "In addition, when the tumor volume exceeded 50 mm3, the numbers of CTCs isolated by GFAP-IMLs were significantly higher than those isolated by the other two IMLs (p < 0.05)." (PMID 33208163, 2020). "We used fluorescence immunohistochemistry (F-IHC) to examine expression of OLIG2, a progenitor marker that was expressed in a majority of PA cancer cells based on scRNA-seq, and of GFAP, a top marker of the AC-like gene programme, in the context of the PA tumor architecture." (PMID 31427603, 2019).
tumor (continued). "Interestingly, the analysis of the dissected GBM xenografts confirmed that Tau is expressed in a high percentage of tumor cells (co-stained with a GFAP antibody) in the Tau-high PDX, whereas there is very little expression in the Tau-low PDX." (PMID 31551755, 2019). "However, in the RC-7-treated mice, the cell mass and GFAP-positive cells were reduced, suggesting that RC-7 was effective at reducing tumor cell growth in vivo." (PMID 31546801, 2019). "Moreover, Western blot analysis demonstrated that AP-2α decreased the expression of Nanog, Sox2 and CD133, and increased the levels of GFAP in both U251 cells and subcutaneous mouse tumor tissues originating from U87 cells." (PMID 31534499, 2019). "GFAP-positive cells were invading the mouse brain parenchyma at the periphery of the tumor mass." (PMID 31779235, 2019). "Tumor cells expressing Olig2, GFAP, or both by F-IHC were observed in all tumors analyzed." (PMID 31427603, 2019). "GBM is a highly heterogeneous tumour consisting of mutant cells that share many antigens such as GFAP with neural stem cells (NSCs), NSC-derived astrocytes and oligodendrocyte precursor cells (OPCs) making it difficult to distinguish from astrocytic cells by the use of antibodies." (PMID 31795330, 2019). "Also important here is the IHC profile diffusely positive for vimentin, with a patchy expression for GFAP, only in the glial component of the tumor." (PMID 31938662, 2019). "Additionally, the GBM stemness was impaired, and complemented with enhanced differentiation, evidenced by the low-level of Nestin and high number of GFAP-expressing cells across the tumor (p < 0.05 and p < 0.01)." (PMID 31380279, 2019). "These regions were smaller and less prominent than in GS tumours, and also showed heterogeneous expression of GFAP, vimentin, EphA2, EphA3 αDG, CD49f and CD31, indicating that this tumour tissue patterning might also occur in GBM (Online Resource 2b)." (PMID 31463571, 2019). "The resected tumor was positive for GFAP, Ki67, vimentin, CD56, and nestin." (PMID 30583471, 2018). "Furthermore, the tumor cells and normal nerve cells exhibited co-expression of nerve markers PGP 9.5, NSE, calretinin, and GFAP, suggesting that the nervous system plays a role in the development of this tumor." (PMID 29329562, 2018). "The original tumor expressed GFAP, which was lost in adherent and R2J spheres." (PMID 30583471, 2018). "Similar to autoimmune encephalitis, GFAP astrocytopathy is also accompanied by a neoplasm." (PMID 30568655, 2018). "This means that they may persist for a long time inside the tumor, often in the form of round, GFAP+ cells." (PMID 30577488, 2018). "GFAP showed patchy, strong cytoplasmic labeling of tumor cells in the astrocytic areas." (PMID 29701169, 2018). "At histological level, these tumors are characterized by their chordoid cellular architecture composed of glial fibrillary acid protein (GFAP)-positive tumor cells, embedded in an extracellular matrix composed by a mixoid matrix, associated with a dense lymphoplasmocytic infiltrate." (PMID 30279357, 2018). "The glial marker GFAP was highly expressed in patient and xenograft tumor." (PMID 29774098, 2018). "Interestingly, NOS2, a target of DUSP4, and DUSP4, both factors that stimulate tumour migration and invasion, are regulated by GFAP." (PMID 29152145, 2017). "The glial marker GFAP was expressed at high levels in the cytoplasm of all tumor cells." (PMID 28103265, 2017). "We found that cells with tumor morphology co-expressed TfR1 and GFAP; additionally we observed co-expression of TfR1 and the stem cell-related markers CD133 and nestin, which is consistent with recently reported data demonstrating that GBM cells co-express TfR1 and the stem cell-related marker SOX2." (PMID 28837569, 2017). "Tumor cells that co-expressed TfR1 and GFAP were also identified." (PMID 28837569, 2017).
tumor (continued). "In our study, TJ905 tumor stem cells were isolated with the magnetic activated cell sorting method and the characteristics of the cancer stem cells were identified using immunofluorescence staining for nestin, β-tubulin, and GFAP." (PMID 28955297, 2017). "Most tumor cells were positive for glial fibrillary acidic protein and S100." (PMID 28320419, 2017). "Early tumor progression was accompanied by an increase in CD9+/GFAP+/SVN+ exosomes." (PMID 29383115, 2017). "In summary, we showed that PLGG tumorigenicity was low despite the presence of putative CSCs, and our data supported GFAP−/Vimentin+ cells, CDKN2A homozygous deletion in trisomy chromosome 9 cells, and BRAF V600E mutation as candidate drivers of tumor progression in the PXA xenografts." (PMID 29152094, 2017). "Finally, a sub-population of tumour cells (accounting for ∼38% of the tumour population) was positive for GFAP, reflecting the astrocytic origin of RG2 tumours." (PMID 28524852, 2017). "For instance, GFAP was associated with tumor volume and histopathological tumor characteristics in GBM, whereas brain metastases did not increase blood GFAP levels." (PMID 28969023, 2017). "Moreover, the fraction of CD9+ exosomes with both GFAP and survivin positivity also showed a significant change at 9 weeks consistent with the patient’s tumor status (p = 0.0225)." (PMID 29383115, 2017). "However, under perfusion, primary GBM cells were not only maintained but demonstrated stable expression of GFAP and a portion of Nanog+ve that would be expected of primary tumours in vivo." (PMID 28842598, 2017). "However, GFAP levels were dramatically decreased in the tumor cells from c-Myc/kRas/Akt3 combination mice." (PMID 26993778, 2016). "Nestin+ TICs, differentiated Tuj1+ neurons and GFAP+ glial cells were detected in the tumor." (PMID 27549983, 2016). "Tumor cells are reactive with GFAP and vimentin, either diffusely or focally." (PMID 27568373, 2016). "To determine whether the tumor cells were expressing markers of differentiation, we analyzed glial fibrillary acidic protein (GFAP) and vimentin at 2, 5 and 10 dpt." (PMID 26659251, 2016). "However, using tumor staining for Olig-2, Nestin and GFAP, we demonstrated that our preclinical model represents a range of GBM cell types, therefore modeling the heterogeneous cell population in human GBM." (PMID 25431423, 2015). "In the present study, U87 spheres were found to be positive for CD133 and nestin; in addition, the cultured tumor spheres were able to differentiate into cells positive for GFAP, β-tubulin III and Galc, therefore suggesting the successful induction of U87 SLCs." (PMID 25760394, 2015). "Nestin was expressed in <50% of the tumor cells with GFAP expressed throughout." (PMID 25919028, 2015). "However, at day 21 the GFAP levels in the tumor increased in both groups, with particularly 1 out of the 3 animals in the differentiated group showed a strong increase in GFAP levels." (PMID 26700636, 2015). "Finally, nestin, NSE and GFAP were used as immunohistochemical markers to compare the degree of tumour differentiation between female and male xenotransplanted mice." (PMID 25000562, 2014). "Focal synaptophysin and fascicles of GFAP-immunopositive tumor were noted." (PMID 24321241, 2014). "Tumor sections were immunostained for Nestin, βIII-Tubulin and GFAP." (PMID 25121761, 2014). "The right portion of the tumor stained positively for collagen type II and the left portion contained neuron-like cells by H&E staining with weak to moderate staining for nestin (70%), βIII-tublin (10%) and GFAP (60%)." (PMID 24670249, 2014).
tumor (continued). "The tumor subspheres expressed GFAP, CD133, Nestin, Nanog, CD44, and CD90." (PMID 24432012, 2014). "A strong expression of GFAP often suggests that tumor cells are mature and well differentiated." (PMID 23590935, 2013). "The transient transfection showed that the GFAP promoter is able to cause luciferase gene expression in GFAP-positive U251 and U87 tumor cell lines, without expression in the GFAP-negative MRC-5 cells." (PMID 23420532, 2013). "Glial fibrillary acidic protein (GFAP) was strongly positive in the tumor cells." (PMID 24381594, 2013). "However, the tumor cells of ECT strongly express GFAP, which is different from the immuno-profile of OFMT." (PMID 23800162, 2013). "As expected, GFAP was highly expressed in the cytoplasm of tumor cells." (PMID 23472076, 2013). "In our tumors, Prom1 was not only expressed by endothelium but also by large GFAP+ tumor cells." (PMID 23637986, 2013). "The prevailing section of the recurrent tumor revealed the strong expression of GFAP and S-100." (PMID 24137435, 2013). "However, the single tumour that grew 10 weeks following internal carotid artery injection of ATCC Walker 256 tumour cells showed an increase in GFAP labelled cells in the peritumoral area and some infiltrating labelled cells within the periphery of the tumour." (PMID 23374226, 2013). "At the tumor border, the vast majority of nestin-positive cell bodies also expressed GFAP." (PMID 22539956, 2012). "All tumors exhibited GFAP expressing cells with great variation in tumor areas." (PMID 22203901, 2012). "These animals reveal GFAP activation with kinetics that is in parallel with tumor growth." (PMID 21247490, 2011). "However, GFAP staining demonstrated that only astrocytes presented an intense nuclear positivity to RECQ1 in tumor tissues." (PMID 21752281, 2011). "C6 cells transfected with GFAP cDNA showed significantly reduced tumor growth." (PMID 20007262, 2011). "The positive immunostaining against GFAP and S-100 supports an astrocytic origin of this tumor." (PMID 22011735, 2011). "Histologically, the tumor cells are polygonal with abundant eosinophilic cytoplasm and eccentric nuclei and on immunostaining, these cells are variably positive for desmin, vimentin, GFAP, CK, EMA, SMA and synaptophysin." (PMID 18439235, 2008). "The tumor cells of GBM are immunoreactive for GFAP and Vimentin." (PMID 15967023, 2005). "Immunoreactivity of tumor cells for GFAP confirms glial differentiation." (PMID 15967023, 2005). "Furthermore, positive immunoreactivity to the S-100 protein and Leu7 antigen tend to indicate the Schwannian nature of the tumour, whereas positivity to the glial fibrillary acidic protein point towards a myenteric plexus origin." (PMID 16026628, 2005). "Remarkably, immunohistochemical analysis verified the extremely low levels of Ki-67 and GFAP markers in tumors of this group, which may indicate a decrease in the tumor cell proliferation rate and the number of reactive astrocytes by intratumoral injection of an oncolytic virus." (PMID 41148834, 2025). "Together, these data suggest that GFAP-positive enteric glia might be associated with tumor localization and median survival but not with other CRC patient characteristics." (PMID 40580485, 2025). "The pathology report revealed an arrangement of cuboidal to elongated tumor cells around hyalinized fibrovascular cores in a papillary fashion, with the accumulation of myxoid material within microcysts, staining positive for GFAP (glial fibrillary acidic protein), and S100 protein." (PMID 40585629, 2025).